TNF (tumor necrosis factor)
Diseases named in the same sentence as TNF in open-access papers (continued):
Sharing a sentence is not in itself a finding about the gene and the disease.
tumor (continued). "This phenomenon increases the immunogenicity of the tumor microenvironment once DAMPs induce the maturation of DCs, and pro-inflammatory cytokines, such as IL-2, IL-6, IL-12, INF-γ and TNF-α, were also reported to increase." (PMID 37238966, 2023). "The data suggest that in the TME of immunotherapy responders, FCRL4+ FCRL5+ B cells are driven by IFNα, TNF, and IL27 signals, and Tfhs are activated by these B cells to enhance anti-tumor immunity through secreting IL21." (PMID 36869384, 2023). "The results of tumor tissue samples showed that the protein levels of chemokines CCL2 and CCL22, as well as TNF-α and IFN-γ, were significantly increased upon TCS treatment." (PMID 36674931, 2023). "Th1 cells secrete cytokines (IL-2, TNF-α, and IFN-γ) that stimulate M1 macrophages, NK cells, and CD8+ T cells to increase the respective anti-tumor activities and prolong cell survival." (PMID 38140230, 2023). "The obtained results revealed significantly elevated levels of TNF-α and TGF-β coupled with higher expression of the MIF mRNA in the DMBA group as compared to the control group confirming the tumor aggressiveness." (PMID 35138531, 2023). "Our data demonstrated LPS‐Nb36 treatment coupled with irradiated DC/HepG2, DC/A549, or DC/MGC-803 fusion cells contributed to an enhanced release of inflammatory mediators (TNF-α, IFN-γ, and IL-2) in contrast to the DC/tumor fusion groups (p < 0.001)." (PMID 37419930, 2023). "Soluble inflammatory mediators and growth factors, such as Interleukin 6 (IL-6), IL-8 and tumor necrosis factor-α (TNF-α) are known to promote cell proliferation, inhibit apoptosis, activate survival pathways, and recruit leukocytes to the tumor site." (PMID 36823670, 2023). "Infected tumor cells secrete cytokines such as type-I IFN and tumor necrosis factor-α (TNF-α), exposing TAAs and viral PAMPs to the host immune system through oncolysis." (PMID 37845388, 2023). "Following tumor recognition, T cells showed increased expression of activation markers (CD137, CD69, IL-2, and TNF-α)." (PMID 37683639, 2023). "systematically investigated the unique and recurrent phenotypes of myeloid across 15 tumor types and identified some potential targets, for example, LAPM3 cDCs and TNF+ mast cells." (PMID 38094301, 2023). "Macrophages can be polarized into M1 through treatment with interferon γ (IFN-γ), tumor necrosis factor α (TNF-α), or lipopolysaccharide (LPS), and they play key roles in innate host defense and kill tumor cells by secreting pro-inflammatory cytokines." (PMID 37375653, 2023). "Recently, several studies have shown that TNF-α promotes metastasis and is involved in EMT, which is necessary for tumor cell migration to establish metastasis." (PMID 37138170, 2023). "Cytokines such as GM-CSF, IL-12,15,18, 23, 24, 36γ, TNF, and IFN-a/b can enhance the anti-tumor response, and tumor lysis has been demonstrated in several studies and clinical trials." (PMID 37631987, 2023). "CD8+ T cells as cytotoxic T lymphocytes play an essential role against virally infected and tumor cells via granule-mediated cytotoxicity, FAS-FASL interaction, and the release of cytokines (e.g. TNF-α and IFN-γ)." (PMID 36707896, 2023). "(C) Circle plot showing the inferred intercellular communication signaling strength network between normal and tumor samples in MHC-II, LAMININ, and TNF pathway (Wilcoxon test, p<0.1)." (PMID 38099574, 2023). "M1 macrophage activation is characterized by high IL‐23 expression levels, and IL‐23 activation allows macrophages to produce tumor necrosis factor (TNF)‐α, an important cytokine for immunogenic tumor cell killing by CD8 + T cells and NK cells." (PMID 38125769, 2023). "By examining the levels of effector molecules (CD69, CD107a, GZMA, IFN-γ, TNF-α, GZMB, and Perforin-1), we also noticed that the tumor-infiltrating CD8+ T cell effector response was significantly enhanced by Rig-I deficiency." (PMID 36927693, 2023).
tumor (continued). "HC release tumor necrosis factor alpha (TNF-α), which stimulates VCAM-1 expression on surrounding endothelial cells, increasing tumor cell migration in situ." (PMID 36968995, 2023). "HF10 induces tumor necrosis, CD8+ cell infiltration, and the release of antitumor cytokines, including IL-2, IL-12, TNF-α, and IFN-α, -β, -γ, to inhibit tumor growth and prolong survival." (PMID 37958464, 2023). "OMV’s stimulate anti- tumor response by secreting cytokines and chemokines like IFN-γ, IL-12p40, CXCL10, TNF- α, IL-6 and have been predicted to be self- sufficient for less destructive tumors like CT26 or MC38 adenocarcinoma." (PMID 38090593, 2023). "CD8+ T cells promote tumor cell death and lysis by secreting perforin, granzyme, IFN, TNF and other mediators, and also promote tumor cell apoptosis by combining FasL with Fas receptor on the tumor cell surface." (PMID 37457707, 2023). "Activated effector CD8+ T cells that recognize tumor antigens can attack and eradicate tumor cells through perforin and granzyme B-mediated cytolysis, Fas/FasL pathway activation, and/or cytokine release (such as IFN-γ and TNF-α)." (PMID 37766136, 2023). "In TLN, Caprin-1 suppressed activation of lymphocytes, T cell activation and anti-tumor cytokine and chemokine (IFNG, IL1B, IL21 and TNF) production." (PMID 38082307, 2023). "Surface-expressed GRP78 was discovered to boost the generation of diverse cytokines with anti-tumor properties, including interferon (IFN)-γ, interleukin (IL)-2, tumor necrosis factor α (TNFα), and granulocyte–macrophage colony-stimulating factor (GM-CSF)." (PMID 37605113, 2023). "Eosinophil commitment to Th1 response was previously shown as well where these leukocytes produced CXCL9, CXCL10, CXCL11, and CCL5 under the effect of TNF-α and IFN-γ, which recruit T and NK cells to eradicate tumor." (PMID 37587450, 2023). "We treated CT26 tumor cells with IFN-γ, and TNF-α followed by treatment with CX3CL1 and obtained comparable results wherein CX3CL1 induced robust expression of genes that promote tumor immune-resistance and generate a pro-metastatic niche." (PMID 37771579, 2023). "To closely follow the course of events, we also tested the serum from ETBF-infected, 086Mut-infected, and sham control 4T1 tumor-bearing mice at day 3 and 4 weeks post-tumor cell implantation for the levels of early-response cytokines, IL6 and TNFα." (PMID 37503343, 2023). "The highest level of TNF-α expression was observed in the ADU-S100 (20 μg) group, which displayed a larger tumor size than the other treatment groups." (PMID 37901237, 2023). "It has been demonstrated that TNF-α and IFN-γ can combine to enhance anti-tumor immunity by activating PANoptosis." (PMID 37501725, 2023). "The expression levels of TNF-α, IL-6 and VEGF were also increased in patients with tumor invasion depth and serosal layer compared with patients without tumor invasion depth (all P < 0.001)." (PMID 37430251, 2023). "Tumor‐infiltrating CD8+ T cells from Tipe2ΔNK/ΔNK mice also displayed increased production of IFN‐γ and TNF‐α compared with those from control mice." (PMID 36807566, 2023). "Senp8mφ–/– mice exhibited excess TNF-α and IFN-γ formation, which is a key factor of the inflammatory process in the tumor microenvironment." (PMID 36626230, 2023). "Traditionally, NK cells target CSCs via two pathways 1) direct NK-cell mediated killing, and 2) induced target tumor differentiation through secreted IFN-γ and TNF-α." (PMID 37954598, 2023). "Thus, the tumor promotion imposed by NKD2 might be through TNF-α/NF-κB signaling pathway." (PMID 36820951, 2023). "Thus, the production of TNFα by tumor or other cells in the microenvironment may, therefore, be an indicator and requirement for responsiveness to IAP inhibitor therapy, which relies on TNFα activation for the induction of apoptosis, necroptosis, and DNA-damage-associated cell death." (PMID 36831373, 2023).
tumor (continued). "Studies on RCC with mutated VHL have shown that proinflammatory cytokines (e.g., IL-6, TNF-α, IL-1) and MMP-2 foster tumor spread and are overexpressed in more invasive cell lines." (PMID 36614308, 2023). "The secretion of cytokines, such as interleukin-2 (IL-2), tumor necrosis factor alpha (TNF-α), interferon-gamma (IFN-γ), and cytolytic granules, such as granzyme B (GB), are the main functional attributes of CD8+ T cells that exhibit anti-tumor activity." (PMID 36798119, 2023). "This GSEA revealed the upregulation of gene sets important for tumor behavior, such as EMT, hypoxia, and TNF-α signaling via NF-κB." (PMID 37434755, 2023). "These pathways contribute to the response to Interferon-gamma, alpha interferon proteins, tumor necrosis factor, transplant rejection, inflammatory response, and KRAS17, indicating a higher level of tumor immune response in the ICD-high subgroup." (PMID 37587188, 2023). "Air pollution–related pro-inflammatory mediators, such as tumor necrosis factor-alpha (TNF-α), interleukin-6 (IL-6), and interleukin-1β (IL-1β), create pro-inflammatory environments that promote tumor development." (PMID 38052753, 2023). "In the case of HeLa cells, they produce proinflammatory cytokines such as TNF-α, IL-6, IL-2, IL-12, and IFN-γ to sustain tumor development and proliferation over the long term." (PMID 37767520, 2023). "In human colorectal cancer, γδ T cells are polarized by microorganisms present due to disruption of the tumor epithelial barrier and inflammatory dendritic cells (Inf-DCs) in the TME to produce cytokines such as TNF-α, GM-CSF, IL-17 and IL-8." (PMID 38077392, 2023). "The alterations in TNF-α signaling, along with the build-up of MDA (malondialdehyde) in the muscle cell bundles, disrupt cellular integrity and promote tumor growth." (PMID 37507468, 2023). "This indirect macrophage-tumor cells cross-talk in treated MTS was paralleled by the secretion of the pro-inflammatory and cytotoxic cytokines (i.e., TNF-α)." (PMID 37346794, 2023). "This approach increases antitumor cytotoxic activity, suppresses tumor growth, and elevates IL-2, IFN-γ, and TNF-α secretions, ultimately improving survival." (PMID 37508372, 2023). "Zhao W and Liu Q mainly study GSK3 by downregulating TNFα-induced GM-CSF by downregulating ERK signaling, thereby driving tumor metastasis by regulating macrophage recruitment and activation." (PMID 38159254, 2023). "Inhibiting CD39 on macrophages significantly increases their production of tumor necrosis factor-α (TNF) and interleukin-12 (IL-12), while decreasing IL-10 secretion, thus inhibiting tumor growth." (PMID 36776866, 2023). "During tumor progression, CAAs support CRC onco-inflammatory milieu through release of proinflammatory cytokines, including IL1-β, IL-6, IL-8, and TNF-α that modulate the innate and adaptive immune response." (PMID 37760840, 2023). "It enhanced the release of immune effector cytokines (IFN-γ, TNF-α, GZMB) in both peripheral and tumor tissue and suppressed Treg cells to improve tumor immunosuppression." (PMID 37397393, 2023). "Meanwhile, TNF-α markedly upregulated p-AKT and p-ERK expressions in tumor tissues, whereas these changes were reversed by MAZ51." (PMID 37124061, 2023). "Similarly, in this study, the tumor tissue sections showed an obvious inflammatory reaction, and changes in the mRNA expression levels of inflammatory response pathway-related molecules and first responders of inflammation, such as NF-κB, TNF-α, and IL-1β, were detected." (PMID 37630266, 2023). "TNF exhibited dual functions in the TME, either as anti-tumor regulator or as an immunosuppressive cytokine, which stimulates examination on its complex role with CRISPR screen." (PMID 37876793, 2023). "CD8+ T cells exert the tumor eradication through the production of cytotoxic molecules, including perforin, granzyme, IFN-γ and TNF-α." (PMID 37853469, 2023).
tumor (continued). "For instance, type I interferons like IFN-β have been shown to increase the tumor cytotoxicity of neutrophils; increase NET, ICAM1 and TNF-α expression; and polarize TANs toward an anti-tumor N1 phenotype in vivo." (PMID 37566060, 2023). "Activated CD8+ T cells, known as CTLs, can induce tumor cell apoptosis by secreting perforin and granase, and kill target cells through the generation of cytokines (IFN-γ and TNF-α) in an indirect manner." (PMID 37419930, 2023). "Tumor necrosis factor (TNF)-related apoptosis-inducing ligand (TRAIL) is a cytokine of the TNF superfamily that plays an important role in apoptosis and tumor surveillance." (PMID 37345089, 2023). "Activated and proliferating lymphocytes secrete interferon-γ (IFN-γ) and tumor necrosis factor-α (TNF-α), which inhibit the proliferation and migration of tumor cells." (PMID 37621681, 2023). "The transfer of the second messenger cGAMP from tumor cells to astrocytes leads to the increased secretion of interferon-α (IFN-α) and tumor necrosis factor-α (TNF-α) by the astrocytes." (PMID 37569410, 2023). "The anti-tumor TANs have higher levels of the C–C motif chemokine CCL3, tumor necrosis factor-α (TNF-α), and intercellular adhesion molecule 1 (ICAM1)." (PMID 37496019, 2023). "In addition, increased expression of tumor-related inflammatory mediators and cytokines, such as TNF-α, IL-1, and IL-6 may stimulate the bone marrow to release neutrophils, resulting in an increase in the circulating neutrophil count and decrease in the circulating lymphocytopenia." (PMID 36899319, 2023). "Tumor necrosis factor (TNF), a major inflammatory cytokine, was initially identified for its capacity to induce rapid hemorrhagic tumor necrosis." (PMID 37915043, 2023). "While TNF-α is a weak stimulator of CCR7 expression, it counterbalances the emergence of M2-like tumor macrophages." (PMID 37415975, 2023). "The combination therapy increased the infiltration of CD8+ T cells, and the percentages of IFNγ+, TNFα+ CD8+ T cells and the percentages of IFNγ+, TNFα+ CD4+ T cells in the tumor microenvironment." (PMID 37553341, 2023). "Other studies have shown that tumor cells that interact with MSC via ligand receptors include SDF-1, VEGF, TNF-α, PDGF, and CXCL16." (PMID 36966336, 2023). "The protein expression of TIM-3, TNF-α, and IFN-γ was assessed in normal tissues, paracarcinoma tissues, and tumor tissues by western blotting, respectively." (PMID 36865498, 2023). "These tumor suppressor cells, such as cytotoxic T lymphocytes, also upregulate the release of pro-inflammatory cytokines, namely, IL-2, IL-6, IL-12, INF-γ, and TNF-α." (PMID 37238966, 2023). "The presence of TIM-1+ B cells decreases the expression of TNF-α and the IFN-γ production of Tc cells and correlates with tumor progression and short survival time." (PMID 37175226, 2023). "TNFα can stimulate a Th1-type immune response, but its presence in the TME of HNSCC tumours has been shown to increase angiogenesis, invasiveness, and metastasis." (PMID 37460712, 2023). "M1 is an anti-tumor and pro-inflammatory macrophage, and it has a critical role to play against pathogens driven by cytokines, such as IFN-ɣ and TNF-α." (PMID 36721212, 2023). "Tumor infiltration by activated immune cells promote secretion of factors such as TGF-β1, TNF-α, and ADAM17 intensifying EMT signals and further driving EMT progression in the cancer cell population, resulting in tumor-promoting positive feedback loop." (PMID 38086828, 2023). "The authors reported an increased expression of CD80 and CD86, meaning an increase in DC maturation, a tumor-inhibiting effect (tumor volume ≈ 0 mm3), and higher levels of INF-γ, TNF-α and IL-6." (PMID 37238966, 2023). "To investigate if ILKAP induces tumor resistance to CTL killing through a mechanism dependent on regulating IFN-γ or TNFα sensitivity, we stimulated ILKAP KO HCT 116 clone with IFN-γ or TNFα." (PMID 37732732, 2023).
tumor (continued). "The CCL2 concentration in tumor homogenates was positively correlated with the level of cytokines with angiogenic activity, such as vascular endothelial growth factor (VEGF), tumor necrosis factor (TNF) α, CXCL8 and thymidine phosphorylase (TP)." (PMID 37208442, 2023). "Recently, the interaction between the tumor and the immune cells has been detected to be modulated by small proteins, as the circulating cytokines TGF-β, TNF-α, and PPAR-γ are detectable in peripheral blood." (PMID 37762927, 2023). "Intriguingly, our investigation into gene expression at the protein level has unveiled increased production of granzyme B, IFN-gamma, TNF-alpha, and soluble Fas ligand (sFasL) pin-transduced TCR-like CAR-T cells upon encountering SK-Mel-37 tumor cells." (PMID 37894816, 2023). "Activation of inflammatory responses releases various growth factors (GFs) and pro-inflammatory cytokines, such as interleukin-6 (IL-6), interleukin-1 (IL-1), and tumor necrosis factor-α (TNF-α), altering catabolism in tumor patients." (PMID 36874094, 2023). "Our previous study showed increased TNF-α expression in IFIT2-depleted metastatic and xenograft-derived sublines, and its inhibition resulted in decreased tumor growth, abolished angiogenic activity, and inhibited metastasis." (PMID 36979874, 2023). "These γδΤ cells then induced the tumor cells to undergo apoptosis by releasing substances such as perforin and granzyme B and by secreting Th1 cytokines IFN-γ and TNF-α." (PMID 37597083, 2023). "Interestingly, several research groups have documented that lycopene could suppress proinflammatory cytokines such as IL-1, IL-1β, IL-6, and TNF-α in several tumor models, including PCa, by downregulating their production and, thus, preventing the inflammatory state." (PMID 36829848, 2023). "Prior to conducting the assay, we identified a subset panel of factors known to mediate the induction of apoptosis in tumor cells: IL-27, IL-1b, IL-2, CXCL10, IL-12p70, G-CSF, IFN-g, TNF-a, IFN-a, CCL2, IL-9, TNF-b, TRAIL, IL-18, IL-21, TSLP." (PMID 37468934, 2023). "NF‐κB also regulates TNF‐α and epidermal growth factor receptor (EGFR), forming a positive feedback regulatory loop between them to promote tumor cell proliferation." (PMID 37547175, 2023). "They found that increased tumor killing also corresponded to an increase in cytolytic cytokines, such as IFN-γ, IL-2, IL-10, TNF-α, sFasL, and granzyme B." (PMID 38136398, 2023). "MSCs have also been shown to promote tumor angiogenesis through release of VEGF, bFGF, FGF-2, IL-8, IL-6, TNF, IGF-1 and TGF β as well as subsequent transformation into smooth muscle cells and pericytes, coupled with formation of new tumor vessels." (PMID 36926687, 2023). "In head and neck cancer cells, the chemokine CXCL14 enhances tumoral infiltration of CD8+ T cells, which trigger the generation of IFN-γ and TNF-α and restore the expression of MHC-I on tumor cells." (PMID 38041084, 2023). "Interestingly, TNFα release could be induced by therapeutic drugs from multiple tumor cell lines." (PMID 37787041, 2023). "TNF-α binds to its receptor TNF-R1 and activates the NF-κB pathway, which regulates several key pathways essential for tumor progression." (PMID 38201482, 2023). "In addition to specifically inducing tumor cell apoptosis, recombinant tumor necrosis factor (TNF)-related apoptosis-inducing ligand (TRAIL) has also been reported to influence the cancer immune microenvironment; however, its underlying effects and mechanisms remain unclear." (PMID 37605148, 2023). "Except that most commonly used for bone metastases tumor biomarkers include bone specific alkaline phosphatase (BALP), tartrate-resistant acid phosphatase (TRACP), tumor necrosis factor (TNF), carbohydrate antigen 15-3 (CA15-3)." (PMID 37404755, 2023).